FOXK2 (forkhead box K2)
Diseases named in the same sentence as FOXK2 in open-access papers (continued):
Sharing a sentence is not in itself a finding about the gene and the disease.
breast carcinoma (continued). "It is important to highlight that FOXK2 has also been shown to play roles in triple negative models of breast cancer, suggesting that it might act independently of ER expression, through a still elusive mechanism." (PMID 30897782, 2019). "However, the experimental settings and the conclusions drawn in each study are supported by in vitro data and further confirm the role of FOXK2 as a tumour suppressor in breast cancer." (PMID 30897782, 2019). "Altogether, this evidence strongly supports a tumour suppressive role for FOXK2 in breast cancer." (PMID 30897782, 2019). "We next performed this set of experiments with the K527/633 R mutant FOXK2 in the triple negative MDA-MB-231 breast carcinoma cells and again found the K527/633 R mutant form of FOXK2 is defective in conferring the cytotoxic/cytostatic functions of paclitaxel in MDA-MB-231 cells." (PMID 29540677, 2018). "In addition, we have also demonstrated that FOXO3 plays a key role in mediating the cytotoxic function of FOXK2 in response to paclitaxel in breast cancer cells." (PMID 29540677, 2018). "Accordingly, FOXK2 mediates drug sensitivity in breast cancer cells in a FOXO3-dependent fashion." (PMID 29540677, 2018). "We have also shown that FOXK2 function is deregulated in drug-resistant breast cancer cells." (PMID 29540677, 2018). "Here, we found that overexpression of a SUMO-defective plasmid impairs the endogenous FOXK2 function in transcription and drug sensitivity in breast cancer cells, confirming FOXK2 as a transcription factor whose transcriptional activity can be stimulated by SUMOylation." (PMID 29540677, 2018). "Furthermore, FOXK2 appeared to suppress ERα-mediated proliferation of breast cancer cells through inhibiting cell cycle progression." (PMID 25740706, 2015). "Taken together, these results suggested that FOXK2 could suppress the growth of breast cancer cells through its modulation of ERα." (PMID 25740706, 2015). "As FOXK2 was able to interact with ERα, and regulate its function, it may in fact affect ERα-mediated proliferation of breast cancer cells, especially since ERα is known to play a major role in the proliferation of breast cancer." (PMID 25740706, 2015). "Considering these observations, we speculated that FOXK2 could have a role in drug resistance in breast cancer." (PMID 26344694, 2015). "Moreover, upon scrutinizing the TCGA database, it was discerned that individuals manifesting elevated levels of FOXK2 expression displayed enhanced responsiveness to conventional breast cancer therapeutics, including cisplatin, lapatinib, talazoparib, and tamoxifen." (PMID 39552461, 2024). "Interestingly, like FOXO3, FOXK2 has been shown to be able to repress breast cancer carcinogenesis." (PMID 32372224, 2020). "In breast cancer, FOXK2 could also mediate epirubicin and paclitaxel resistance via FOXO3a." (PMID 33313412, 2020). "Additionally, it would be of importance to examine whether these FOXK2 residues are found SUMOylated in breast cancer patients." (PMID 29540677, 2018). "We also showed that FOXK2 could suppress ERα-mediated proliferation of breast cancer cells." (PMID 25740706, 2015). "However, little is known about the role of FOXK2 in tumorigenesis of breast cancer." (PMID 25740706, 2015). "Given that there was a negative correlation between ERα and FOXK2 in human breast cancer, we speculated that there may be a causal relationship between FOXK2 and ERα at the protein level." (PMID 25740706, 2015). "Compared with HER2+ and HR+ breast cancers, FOXA1 was lowly expressed in TBNC, while FOXC1, FOXK2, and FOXM1 were highly expressed." (PMID 36292640, 2022). "FOXK2 functions as oncogene in HCC and colorectal cancer or tumor suppressor in NSCLC, glioma, breast cancer and renal cell carcinoma." (PMID 33313412, 2020). "FOXK2 has also been found to regulate FOXO3 expression at the transcriptional level to mediate the cytotoxic effects of epirubicin and paclitaxel in breast cancer." (PMID 32372224, 2020).
breast carcinoma (continued). "We found that, compared with the wild-type FOXK2, both the SUMO-mutants (i.e., K527/633 R and E529/635 A) are defective in mediating the paclitaxel-induced cytotoxicity in breast cancer cells." (PMID 29540677, 2018). "Here, we report that FOXK2 is modified by SUMOylation and overexpression of a SUMOylation-defective form of FOXK2 prevents endogenous FOXK2-mediated induction of FOXO3 expression and confers paclitaxel resistance to drug-sensitive breast cancer cells." (PMID 29540677, 2018). "In the presence of paclitaxel or epirubicin treatment, clonogenic and cell viability assays showed that enhanced expression of FOXK2 inhibits cell proliferation and clonogenic growth of the drug-sensitive MCF-7 breast carcinoma cells." (PMID 26344694, 2015). "SUMOylation might act to enhance FOXK2 transcriptional activity and mediate the cytotoxic response to paclitaxel through the tumour suppressor FOXO3 in breast cancer." (PMID 36172141, 2022). "The interaction of FOXK2 may be prevented by the cytoplasmic localization of SIN3A p.Gln944*, and thus may cancel the growth inhibition of breast cancer cells." (PMID 30375428, 2018). "In addition, breast cancer cells overexpressing the mutant form of FOXK2 had substantial lower protein and mRNA expression levels of FOXO3 when compared with wild-type FOXK2." (PMID 29540677, 2018). "Together, these data show that FOXK2 can directly bind to the FOXO3a promoter and regulate its expression in the paclitaxel-sensitive, but not the resistant, breast cancer cells." (PMID 26344694, 2015). "We also obtained results to suggest that FOXK2 is predominantly located in the nucleus of breast cancer cell lines, regardless of their drug resistance and treatment." (PMID 26344694, 2015). "In breast cancer cells, FOXA1 and FOXO3a can regulate the function of ERα via their FOX domains, and since FOXK2 also contains a conserved FOX domain, we speculated that it too may interact with ERα." (PMID 25740706, 2015). "We also present compelling evidence to show that drug-resistant breast cancer cells are able to tolerate high levels of nuclear FOXK2 because FOXK2 is deregulated and fails to be recruited to targets genes, such as FOXO3a." (PMID 26344694, 2015). "Taken together, these results suggested that a negative correlation existed between ERα and FOXK2 in breast cancer." (PMID 25740706, 2015). "In breast cancer, 53 breast tumor specimens (27 ERa-positive and 26 ERa-negative) were analyzed using immunohistochemical assays, and a negative correlation between ERa and FOXK2 was observed." (PMID 36172141, 2022). "For example, FOXK2 was shown to promote tumor progression by interacting with Dishevelled (DVL) and activating Wnt signaling in colon cancer models, but suppressed estrogen receptor–positive breast cancer cell proliferation by interacting with transcriptional corepressor complexes." (PMID 35349489, 2022). "In this report, we observed a negative correlation between ERα and FOXK2 in human breast cancer." (PMID 25740706, 2015). "Notably, these cytotoxic effects of FOXK2 were observed in both MCF-7 and MDA-MB-231 cell lines, which resemble different breast cancer molecular subtypes, suggesting that this mechanism of FOXK2 regulation is independent of expression of estrogen, progesterone and Her2 receptors." (PMID 29540677, 2018). "The levels of FOXK2 expression in the ERα-positive breast cancer cell lines (MCF-7, T47D, ZR-51-30 and BT474) were significantly lower than that in ERα-negative breast cancer cell lines (MDA-MB-231 and Bcap-37)." (PMID 25740706, 2015).
colorectal cancer (14 papers, 2017 to 2024). A primary or metastatic malignant neoplasm that affects the colon or rectum. "The presence of FOXK2 is linked to the metastasis of colorectal cancer, and the drug cetuximab can disrupt the feedback loop involving EGF NF‐κB–FOXK2–EGFR, thus preventing metastasis in CRC." (PMID 39552461, 2024). "In human colorectal cancer, FOXK2 also exhibits a positive feedback loop as a regulatory factor in the cell cycle and tumor progression." (PMID 38741782, 2024). "There is more FOXK2 expression in colorectal cancer tissues than in normal tissues, and in metastatic tissues than in primary tissues, and in primary tissues of metastatic patients than in non-metastatic patients, which is associated with poor prognosis." (PMID 35903069, 2022). "FoxK2 is significantly upregulated in human colorectal cancer tissues, which correlates with aggressive characteristics and suggests a poor prognosis." (PMID 35903069, 2022). "Low expression of the UTP6 was found to be associated with chemoradiotherapy resistance and the prognosis of colorectal cancer possibly via regulating FOXK2 expression by transcription factor pathways." (PMID 34485268, 2021). "The forkhead box K2 protein (FOXK2) promotes colorectal cancer metastasis by upregulating mRNA expression of zinc finger E-box binding homeobox 1 (ZEB1)." (PMID 32194639, 2020). "EGFR was upregulated by FOXK2 in colorectal cancer to enhance the metastasis of colorectal cancer cells." (PMID 32231464, 2020). "The gene targets involved in mediating FOXK2 oncogenic effects in colorectal cancer remain to be determined." (PMID 30897782, 2019). "The same pattern of differential expression of FOXK2 has been found in a cohort of colorectal cancer, with a 49% high staining positivity." (PMID 30897782, 2019). "Corroborating these data, Qian and colleagues have reported that FOXK2 promotes proliferation of colorectal cancer cell lines and has its promoter transcriptionally regulated by the sex-determining region Y box 9 (SOX9) oncogenic protein." (PMID 30897782, 2019). "Furthermore, SOX9, another regulatory factor, can bind to the promoter sequence of FOXK2 and activate its transcriptional expression, directly participating in the initiation and progression of colorectal cancer." (PMID 38741782, 2024). "Overexpression of FoxK2 promotes migration, invasion, and metastasis of colorectal cancer." (PMID 35903069, 2022). "Colorectal cancer is influenced by both FoxK1 and FoxK2, with they all promoting the tumor." (PMID 35903069, 2022). "In addition to colorectal cancer, FOXK2 has also been shown to act as an oncogene in hepatocellular carcinoma (HCC), in which it has been demonstrated to promote cell migration and proliferation with the involvement of the PI3K/AKT signaling pathway." (PMID 30897782, 2019). "However, in colorectal cancer, FOXK2 operates as an oncogene and is activated by NFkB signaling." (PMID 36009586, 2022). "In colorectal cancer, Sox9 could activate FOXK2 and further promote the tumor cell multiplication." (PMID 33313412, 2020). "For example, SOX9 transcriptionally activated FOXK2, which belongs to the fork head DNA binding protein family, has been shown to play a critical role in tumorigenesis, high expression of FOXK2 is significantly correlated with poor survival of colorectal cancer." (PMID 29348895, 2017). "Subsequently, FOXK2 activates the transcription of EGFR and ZEB1, crucial regulators of the epithelial-mesenchymal transition (EMT), invasion, and metastasis in colorectal cancer." (PMID 38741782, 2024). "FOXK2 can also transcriptionally activate EMT and drive transcription factor ZEB1 to promote EMT and invasion and metastasis of colorectal cancer." (PMID 35903069, 2022). "For instance, FOXK1 and FOXK2 were shown to induce nuclear translocation of DVL and to activate WNT/β-catenin signaling in colorectal cancer." (PMID 35349489, 2022).
colorectal cancer (continued). "FOXK1 was highly expressed in colorectal cancer, and FOXK1 and FOXK2 transfered DVL (Dishevelled)-related proteins into the nucleus, which positively regulated Wnt/β-catenin signaling pathway." (PMID 30744670, 2019). "Altogether, these studies clearly link the FOXK2 transcription factor to a poor outcome in HCC and colorectal cancer patients." (PMID 30897782, 2019). "For example, in colorectal cancer, FOXK1 acts as a DVL-interacting protein, and transfers DVL-related proteins into the nucleus with FOXK2, which positively regulates the Wnt/β-catenin signaling pathway." (PMID 30744670, 2019). "Notably, FOXK2’s regulation on EGFR can be context-dependent and cell-specific; it functions as a tumor suppressor gene in ccRCC by inhibiting EGFR and inducing apoptosis, contrasting its role in colorectal cancer." (PMID 38741782, 2024).
hepatocellular carcinoma (9 papers, 2019 to 2024). A malignant tumor that arises from hepatocytes. "Elevated FOXK2 SUMOylation causes resistance to 5-FU in hepatocellular carcinoma." (PMID 39108750, 2024). "Meanwhile, down-regulation of miR-1271-5p alleviates FOXK2 inhibition in hepatocellular carcinoma cells, facilitating tumor growth and metastasis through the PI3K/AKT signaling pathway." (PMID 38741782, 2024). "We also examined the expression of FOXK2, which has previously exhibited reciprocal expression with miR-1271-5p in hepatocellular carcinoma tissue, but we were unable to replicate this in SH-SY5Y cells." (PMID 32325711, 2020). "Furthermore, FOXK2 is significantly upregulated in hepatocellular carcinoma (HCC) cells." (PMID 38741782, 2024). "However, functional and regulating mechanisms of FOXK2 in epithelial–mesenchymal transition (EMT) in hepatocellular carcinoma (HCC) remain unclear." (PMID 33313412, 2020). "In NSCLC cells, FOXK2 inhibits EMT through the PI3K-Akt pathway, contrasting with its promoting role in hepatocellular carcinoma cells." (PMID 38741782, 2024). "In hepatocellular carcinoma (HCC), FOXK2 is a direct target of miR-1271." (PMID 36172141, 2022). "FOXK2 increased cell proliferation and migration by activating the PI3K/AKT pathway in hepatocellular carcinoma." (PMID 35349489, 2022). "Additionally, FOXK2 protein and mRNA levels have been found upregulated in hepatocellular carcinoma, compared to non-tumorous liver counterpart." (PMID 30897782, 2019). "Moreover, FOXK2, one of the two members of FOXK family, which collaborated with FOXK1 and showed the similar capability in a few physiological and pathological processes, has been demonstrated to change the phosphorylated status of AKT and exert oncogenic function in hepatocellular carcinoma." (PMID 32363163, 2020).
lung cancer (9 papers, 2016 to 2025). A malignant neoplasm involving the lung. "The results showed that FBXO32 and FOXK2 were significantly co‐expressed in epithelial cells of lung cancer STAD, and BLCA." (PMID 39552461, 2024). "Previous studies demonstrated that FOXK2 suppressed the growth of lung cancer cells by targeting cyclin D1 and CDK4 and also influenced CDKs, which linked it to the regulation of the cell cycle." (PMID 33251211, 2020). "In cell line models of human embryonic kidney and lung cancer, FOXK2-mediated recruitment of BAP1 to target genes has been confirmed by another study, which identified Thr493 as the phosphorylation site of BAP-1 and that this site is necessary for interaction with the FHA domain of FOXK2." (PMID 30897782, 2019). "This places epigenetic modifications as additional mechanisms for silencing FOXK2 gene expression, which might have implications for the pathogenesis of lung cancer." (PMID 30897782, 2019). "FOXK2 is highly expressed in chronic lymphocytic leukemia (CLL), metastatic breast cancer (MBC), and osteosarcoma clusters and corresponds to poor outcomes in melanoma and non‐small cell lung cancer (NSCLC) cohorts." (PMID 39552461, 2024). "Specifically, FOXK2 was found to be significantly overexpressed in tumor tissues of prostate adenocarcinoma (PRAD), endometrial cancer (UCEC), BLCA, CRC, pancreatic duct adenocarcinoma (PDAC), STAD, lung cancer, and thyroid cancer." (PMID 39552461, 2024).
glioma (8 papers, 2019 to 2024). A benign or malignant brain and spinal cord tumor that arises from glial cells (astrocytes, oligodendrocytes, ependymal cells). "Similar conclusions have been derived from FOXK2 knockdown studies, where loss of FOXK2 promotes growth, invasion and migration in glioma cells, followed by modulation of expression of E-cadherin, N-cadherin and vimentin EMT markers." (PMID 30897782, 2019). "Similar to the case in gastric cancer, FOXK2 expression gradually decreased with increasing glioma grades, and low FOXK2 was indicative of poor prognosis." (PMID 36172141, 2022). "FOXK2 mRNA expression has been found to be downregulated in high-grade, compared to low-grade glioma." (PMID 30897782, 2019). "Furthermore, FOXK2 expression is inversely correlated with gastric cancer and glioma grade as well as prognosis." (PMID 38741782, 2024). "However, further exploration is required to understand the regulatory mechanisms of FOXK2 in gastric cancer and glioma." (PMID 38741782, 2024). "In glioma, FOXK2 could inhibit the cell multiplication and motility and predict a favorable prognosis." (PMID 33313412, 2020). "Previous research studies have revealed that the FOXK2 suppressed EMT in NSCLC and glioma via suppression of various pivotal target genes." (PMID 33313412, 2020).